TF (transferrin)
Diseases named in the same sentence as TF in open-access papers (continued):
Sharing a sentence is not in itself a finding about the gene and the disease.
iron deficiency (continued). "The sequencing results revealed a significant increase in the expression of HIF1 and TF in the AD group, indicating a strong correlation between iron deficiency and HIF1 expression." (PMID 38886644, 2024). "Intranasal holo‐transferrin (hTF) administration bypassing the BBB alleviates oligodendrocyte iron deficiency and promotes myelin regeneration in hypoperfusion‐induced white matter injury." (PMID 39161089, 2024). "We designed a single-arm pilot study to evaluate the efficacy of liposomal iron administered for six months in correcting iron deficiency (defined as serum ferritin < 100 ng/mL and/or transferrin saturation < 20%) in patients with NDD-CKD stages 1–5." (PMID 38732502, 2024). "Considering the decreasing levels of hemoglobin and grip strength and the high prevalence of iron deficiency in older adults further analyses investigating this relationship with more iron specific parameters such as transferrin saturation are warranted." (PMID 38451343, 2024). "The human aortic protein was extracted for Western blot analysis, which revealed an up-regulation of TF expression in response to iron deficiency and significant alterations in indices associated with AD." (PMID 38886644, 2024). "Instead, we found that a higher body mass index was associated with a higher risk for functional iron deficiency and lower transferrin saturation." (PMID 39316402, 2024). "To conclude, relevant data on ferritin and transferrin reference values and prevalence of iron deficiency for European children is scarce, particularly for those children above the age of 3 y and for relevant subgroups such as obese and nonobese children." (PMID 38048991, 2024). "Transferrin is a marker of iron-binding capacity produced by the liver in response to iron deficiency." (PMID 39191894, 2024). "Iron deficiency is defined as a ferritin level <12 μg/L in children aged <5 years old or <15 μg/L in children aged ≥ 5 years old or serum transferrin > 8.3 mg/L." (PMID 39457233, 2024). "The five patients with iron deficiency had a mean serum iron level of 4.4 ± 1.2 μmol/L, a mean transferrin level of 3.06 ± 1.16 g/L, and an average total capacity of transferrin of 76.2 ± 29.1 μmol/L." (PMID 38287291, 2024). "A total of 80 (45.2%) patients had iron deficiency, 15 (8.5%) had sufficient ferritin and transferrin saturation, and 82 (46.3%) had incomplete iron status samples." (PMID 39408062, 2024). "The SNP rs3811647 in the TF gene was investigated in six studies, all of which indicated a greater risk for iron deficiency." (PMID 39599580, 2024). "In cases of chronic inflammatory conditions, serum ferritin concentration as high as 100 μg/l or serum transferrin saturation of less than 20% are considered diagnostic for iron deficiency." (PMID 38407751, 2024). "If iron deficiency is identified (transferrin saturation level ≤30% and a ferritin level ≤500 ng/mL), iron repletion is recommended and can sometimes require the use of IV iron infusions." (PMID 39124645, 2024). "Functional iron deficiency was defined as serum ferritin greater than or equal to 30 ng/mL with transferrin saturation less than 20%." (PMID 39316402, 2024). "There were more females that met the criteria for the three measurements of iron deficiency: ferritin (168 females, 13 males), serum iron (154 females, 49 males), and transferrin saturation (120 females, 22 males)." (PMID 38226328, 2024). "The most likely cause for severe microcytic anaemia in this patient was iron deficiency, as confirmed by a transferrin saturation of 19% (reference range 20–50%)." (PMID 39171138, 2024). "Higher body mass index was associated with a higher risk of functional iron deficiency compared with iron replete status and with a lower transferrin saturation (eTable 4 in Supplement 1)." (PMID 39316402, 2024). "After conducting a series of tests, including ferritin, serum iron, transferrin, and a bone marrow examination, she was diagnosed with iron deficiency anemia (IDA)." (PMID 39867693, 2024).
iron deficiency (continued). "The problem of overordering plasma transferrin measurements in iron deficiency anemia was illustrated using a flowchart." (PMID 38447167, 2024). "Functional iron deficiency is characterized by a reduction in transferrin saturation associated with replenished iron deposits (normal or increased serum ferritin), which are not immediately available for erythropoiesis." (PMID 38732502, 2024). "In line with our findings derived from human sequencing data, both HIF1 and TF expressions exhibited a significant up-regulation in the context of iron deficiency." (PMID 38886644, 2024). "Given that iron deficiency up-regulated transferrin as reported, the host-driven iron withdrawal upon microbial infection likely expands transferrin’s up-regulation induced by microbial products." (PMID 38274126, 2024). "Its hepatic synthesis is regulated by the body’s iron status; more transferrin is synthesized in iron deficiency to allow more iron transport." (PMID 39451629, 2024). "Conventionally, iron deficiency diagnosis is based on determining ferritin, transferrin saturation, and soluble transferrin receptor, but these biomarkers are strongly influenced by inflammation and infection." (PMID 38435983, 2024). "Both intravenous iron compounds were associated with resolution of iron deficiency by the end of the trial period, with significant improvements in serum ferritin, transferrin saturation and hemoglobin concentration." (PMID 38347520, 2024). "After 3-months' follow-up, the proportion screened for iron deficiency was 11.2% based on transferrin saturation and 33.7% using serum ferritin." (PMID 38092441, 2024). "A previous clinical study involving 62 patients with RA indicated that over 60% of patients exhibited iron deficiency, characterized by lower ferritin and transferrin levels." (PMID 39345879, 2024). "If iron deficiency anemia is defined as the increase in hemoglobin level to the administration of iron, transferrin saturation is a more efficient predictor of “iron deficiency anemia” than ferritin level." (PMID 38941000, 2024). "In a Norwegian sample of 6–12-y-old children, the prevalence of iron deficiency as well as mean serum ferritin and transferrin were similar to our study." (PMID 38048991, 2024). "People with all four hemoglobin, iron, ferritin, and transferrin saturation values lower than normal ranges at the same time were considered to have iron deficiency anemia." (PMID 39685501, 2024). "TS% is a measure of the iron carrying capacity of transferrin, abnormally low TS% being indicative of iron deficiency which can lead to anaemia, while abnormally high levels can be a sign of iron overload." (PMID 39191894, 2024). "It has been reported that in cases of iron deficiency, plasma transferrin concentration increases and transferrin saturation decreases." (PMID 38407751, 2024). "It was previously recommended that all patients with HF undergo screening for iron deficiency with baseline labs including complete blood count, ferritin, and transferrin saturation." (PMID 37383191, 2023). "Iron deficiency in patients with HF is defined as either serum ferritin concentration of <100 ng/mL or 100-299 ng/mL with transferrin saturation (TSAT) <20%." (PMID 37965394, 2023). "Transferrin saturation (Tfsat) levels have been widely used to characterize iron metabolism disorders, because low or high Tf saturation levels indicate iron deficiency or iron overload conditions, respectively." (PMID 38067440, 2023). "Women tend to be more affected by iron deficiency (ferritin < 15 μg/l) and iron insufficiency (transferrin saturation < 16%) than men." (PMID 38017527, 2023). "Our meta-analysis confirmed that single dose of intravenous iron isomaltoside ferumoxytol and repeated doses of oral iron sucrose resulted in comparable Hb change, serum ferritin and transferrin saturation for the treatment of iron deficiency anemia." (PMID 38357109, 2023).
iron deficiency (continued). "A reduced transferrin saturation is a marker of iron deficiency, though can also occur with chronic inflammatory disease." (PMID 36823529, 2023). "Iron deficiency is defined by current clinical guidelines as a serum ferritin concentration <100 ng/mL or a serum ferritin <300 ng/mL with transferrin saturation <20%." (PMID 37374094, 2023). "Approximately 26% of the study participants demonstrated transferrin saturation (TfS) < 20%, and 20% had ferritin <10–15 ng/mL, which together indicates age-related iron deficiency." (PMID 37240288, 2023). "Serum TIBC, which indicates levels of total transferrin and increases during iron deficiency, tended to be higher in the FEMT than in the FE group at intervention week 4 and 6 (P = 0.052 and P = 0.083, [GLMM], respectively)." (PMID 37480367, 2023). "Use serum ferritin, CRP, transferrin saturation and serum iron to assess presence of iron deficiency and haemoglobin, blood count and other micronutrients when diagnosing iron deficiency anaemia." (PMID 35735908, 2023). "For example, we were unable to account for iron deficiency as a confounder because serum ferritin and transferrin saturation were only measured in a small subsample of study participants." (PMID 37768811, 2023). "Iron deficiency anemia was identified through serum ferritin <100 ng/mL, transferrin saturation <20%, and hematologic parameters." (PMID 38149144, 2023). "The anemic rats developed iron deficiency anemia with lower iron and higher transferrin levels (68.1 ± 22.6 μg/dL vs. 182.8 ± 70.7 μg/dL, p < 0.001; 170.5 ± 35.3 mg/dL vs. 120.2 ± 22.1 mg/dL, p < 0.01), respectively." (PMID 37760779, 2023). "In this report, we explored the association between LRG1 and anemia in school-aged children by assessing the correlation between LRG1 and several iron deficiency markers, including Hb, iron, percentage of transferrin saturation, albumin, and RDW." (PMID 37513518, 2023). "Several published reports indicate that serum iron and transferrin saturation are biochemical markers of iron status that are used in iron deficiency diagnosis." (PMID 37513518, 2023). "On the contrary, transferrin saturation less than 20% indicates iron deficiency and more than 45% suggests iron overload." (PMID 38068803, 2023). "Further, osteocytes directly controlled HIF-dependent FGF23 production via interactions with holo-transferrin during mimicked iron deficiency." (PMID 36650133, 2023). "The low value of transferrin is an indicator of iron deficiency anemia and vice versa is the overload of iron or hemochromatosis." (PMID 37384107, 2023). "26% of individuals demonstrated transferrin saturation TfS < 20%, which clearly indicates age-related iron deficiency." (PMID 37240288, 2023). "Iron deficiency and anemia, as well as iron overload, are the result of impaired iron metabolism, in which a number of proteins, such as hepcidin, hemojuvelin and transferrin, take part." (PMID 36986181, 2023). "Another candidate for a serum marker of malnutrition is transferrin; however, there are similar limitations with regard to the interpretation of its serum level—it is increased in iron-deficiency status and in renal failure." (PMID 37836461, 2023). "Absolute iron deficiency was defined as ferritin <30 μg.l−1; functional iron deficiency as ferritin 30–100 μg.l−1 or transferrin saturation < 20%; and the remainder as non‐iron deficient." (PMID 36477695, 2023). "For example, while alcoholics are reported to have high serum ferritin and transferrin saturation, we still observe high prevalence of iron deficiency and iron deficiency anemia in these patients." (PMID 37547205, 2023). "FIT enrolled 202 patients with anemia defined as WHO definitions and iron deficiency defined as transferrin saturation (TSAT) < 20% who underwent curative resection for colorectal cancer." (PMID 37754484, 2023).
iron deficiency (continued). "The most frequently used definition of iron deficiency in patients with cardiovascular disease is ferritin < 100 μg/L or ferritin 100–299 μg/L and transferrin saturation (TSAT) < 20%41." (PMID 36261681, 2022). "A few studies have been recently conducted which have indicated that serum transferrin is a reliable and useful indicator for diagnosis of iron deficiency anemia specifically in individuals suffering from malaria or other infections." (PMID 35844906, 2022). "Increased serum transferrin level is often observed in people with iron deficiency anemia, which is tightly associated with autism and other neurological diseases." (PMID 36407516, 2022). "It was demonstrated in experimental researches that RDW first became abnormal than other measures including hemoglobin, MCV and transferrin saturation as iron deficiency anemia (IDA) developed, suggesting an early biochemical clue." (PMID 35755057, 2022). "Taking into consideration these data, it is advisable to proactively search for iron deficiency by assessing serum levels of iron, transferrin and ferritin in patients with PA, in particular when the typical macrocytosis (MCV > 100 fL) is not present." (PMID 35458234, 2022). "Iron deficiency, as indicated by low serum ferritin (12 μg/dL) and serum transferrin (< 2.0 g/L), was present in 13% and 2.9% of children, respectively." (PMID 36337439, 2022). "Iron deficiency is treated based on a serum ferritin level of <100μg/L or 100-299μg/L when transferrin saturation is <20%." (PMID 35178308, 2022). "For example, in situations of iron deficiency, the liver produces more transferrin, increasing the blood’s total TIBC." (PMID 36139084, 2022). "Serum levels of ferritin, transferrin saturation, and muscle iron content were lower in the iron deficiency than in non-iron deficiency patients, while those of the soluble transferrin receptor and transferrin were higher in the former patients." (PMID 36235581, 2022). "CHr is considered a more sensitive marker for iron deficiency and changes earlier than ferritin or transferrin saturation." (PMID 35177695, 2022). "Iron overload leads to an increase in serum iron, ferritin, and transferrin saturation but a decrease in transferrin, whereas iron deficiency shows the opposite trends." (PMID 36568116, 2022). "Using a diagnostic threshold of ferritin level less than 100 ug/L, or a combination of a ferritin level between 100 and 299 ug/L and transferrin saturation under 20%, these investigators found that 47.6% of individuals with AF had iron deficiency." (PMID 35508964, 2022). "Low ferritin values, as a part of the iron deficiency definition used in the study (ferritin < 100 μg/L or transferrin saturation < 20%), had a protective effect, with a reduced composite outcome of in-hospital mortality and Killip class ≥ 3 (p = 0.01)." (PMID 35204567, 2022). "To evaluate the prognostic value of transferrin as a marker of functional iron deficiency in malignancy, we calculated the AUC, sensitivity, and specificity of the test using ROC analysis." (PMID 36555993, 2022). "The aim of our study was to assess the role of transferrin in the prognosis of cancer of the ovary and related iron deficiency." (PMID 36555993, 2022). "Functional iron deficiency in patients diagnosed with ovarian cancer is associated with decreased serum transferrin levels." (PMID 36555993, 2022). "Diagnosis of iron deficiency is based on low serum ferritin and reduced transferrin saturation (TSAT)." (PMID 35895618, 2022). "Decreased transferrin saturation or increased soluble transferrin receptor (sTfR) portrays the second stage of iron deficiency, reflecting reduced erythropoiesis." (PMID 35807896, 2022). "Transferrin, in our study, showed a high potential as a biomarker of functional iron deficiency and CRA." (PMID 36555993, 2022).
iron deficiency (continued). "For example, iron deficiency affects the expression of transferrin (Tf), which is one of the most highly upregulated genes dur-ing this period, and controls the expression levels of several key myelination proteins." (PMID 36141325, 2022). "Iron deficiency is defined as a ferritin level of <100 μg/L or ferritin level between 100-299 μg/L with transferrin saturation of <20%." (PMID 35178308, 2022). "Iron deficiency (measured by transferrin saturation—TSAT) was associated with poor outcome in patients with pancreatic, colorectal, and lung cancers." (PMID 36551774, 2022). "Iron deficiency was defined as a ferritin level <100 ng/mL or a transferrin saturation <20% and a ferritin level 100 to 299 ng/mL." (PMID 35971840, 2022). "As diagnosing IRIDA can be challenging due to its genotypical and phenotypical heterogeneity, we assessed the transferrin saturation (TSAT)/hepcidin ratio to distinguish IRIDA from multi-causal iron deficiency anemia (IDA)." (PMID 35163840, 2022). "The 2021 guidelines for the diagnosis and treatment of heart failure endorsed by the European Society of Cardiology (ESC) advocated screening for iron deficiency (including ferritin and transferrin saturation) with class IC recommendation." (PMID 35204567, 2022). "The European guidelines recommend that HFrEF patients should be tested for anemia and iron deficiency using serum ferritin and transferrin saturations." (PMID 35892914, 2022). "Unequivocally, disorders of iron metabolism, including iron deficiency and overload, and corresponding representing markers such as serum iron, ferritin, transferrin, and transferrin saturation (TSAT), closely relate with numerous cancer." (PMID 36568176, 2022). "The subjects were 40 systolic heart failure patients (ejection fraction ≤35%) with anemia, iron deficiency (serum ferritin <100 μg/L and/or transferrin saturation <20%), and mild renal dysfunction." (PMID 35178308, 2022). "Association between transferrin saturation and ferritin at different cut-offs in assessing iron deficiency." (PMID 36240192, 2022). "We used ferritin, transferrin and sTfR proteins as biomarkers for diagnosis of iron-deficiency anemia in schoolchildren." (PMID 35245314, 2022). "In general, transferrin is increased in absolute iron deficiency to maximize the use of the limited available iron." (PMID 35034629, 2022). "For this study, iron deficiency was defined as serum ferritin < 30μg/L or ferritin < 100μg/L and transferrin saturation <20%." (PMID 35895618, 2022). "This complements our findings, as high TIBC is an indicator of iron deficiency and means that there are higher concentrations of circulating free transferrin due to low concentrations of circulating free iron to bind." (PMID 35538408, 2022). "Ferritin and transferrin saturation are blood markers that can be used for the diagnosis of iron deficiency." (PMID 35178308, 2022). "Additional iron studies including transferrin saturation, vitamin B12 and folate should be collected to determine the cause of non-iron deficiency anaemia." (PMID 35922876, 2022). "The management of posttransplant iron deficiency is complicated by uncertainty about the target hemoglobin, iron deficiency measures such as ferritin or transferrin saturation, and the role of erythropoietin." (PMID 35795334, 2022). "Iron deficiency in HF has been defined as serum ferritin concentration < 100 μg/l, or ferritin concentration between 100 and 300 μg/l, along with transferrin saturation (TSAT) of < 20%." (PMID 34584938, 2021). "Iron deficiency is diagnosed by the presence of low serum iron levels (less than 50 μg/dl) and high serum transferrin levels." (PMID 34067622, 2021). "According to USPSTF review, there is a lack of data evaluating the sensitivity and specificity of other single tests for the detection of iron deficiency, such as serum ferritin, transferrin saturation, erythrocyte protoporphyrin, and CRP." (PMID 34496786, 2021).